SCN2A (sodium voltage-gated channel alpha subunit 2)
Diseases named in the same sentence as SCN2A in open-access papers (continued):
Sharing a sentence is not in itself a finding about the gene and the disease.
schizophrenia (20 papers, 2015 to 2025). A major psychotic disorder characterized by abnormalities in the perception or expression of reality. "The schizophrenia proband who had this SCN2A missense variant developed psychotic symptoms at an early age of 14 years, but does not have a learning disability or comorbid ASD." (PMID 34504065, 2021). "In one study assessing the effects of different SCN2A variants in schizophrenia, postmortem examination of SCN2A expression in the prefrontal cortex revealed that lower levels of SCN2A expression were associated with poorer cognitive performance." (PMID 32264956, 2020). "Polymorphisms of SCN2A, the gene encoding Nav1.2, are associated with the occurrence of schizophrenia." (PMID 31920555, 2019). "Although this gene has not been highlighted in earlier BPD studies, de novo mutations in SCN2A were found associated with autisms, and common variations within or near this gene were also associated with cognitive performance in schizophrenia patients." (PMID 30531795, 2018). "Furthermore, SCN2A is associated with psychiatric disorders such as bipolar disorder and schizophrenia." (PMID 39228919, 2024). "Moreover, the sodium channel, voltage-gated type II α subunit gene SCN2A, has been shown to exhibit mutations in schizophrenia." (PMID 35062349, 2022). "For example, the SCN2A and GSK3B genes are associated with major depressive disorder and schizophrenia in the Han Chinese population." (PMID 39452151, 2024). "Bilateral injections of adeno-associated virus (AAV) expressing Cre recombinase were injected into Scn2afl/fl mice to selectively delete Scn2a from mPFC or VTA to elucidate the role of Nav1.2 in schizophrenia." (PMID 39606727, 2024). "Subsequent fMRI studies showed that the SCN2A SNP rs10174400 is a significant predictor of cognitive ability not only in schizophrenia patients but in healthy adults as well." (PMID 32264956, 2020). "In vitro electrophysiological studies have shown that the different epileptic phenotypes may be caused by either gain- or loss-of-function SCN2A mutations, whereas it has been proposed that ASD, and possibly also ID or schizophrenia, arise from loss-of-function mutations." (PMID 31501495, 2019). "Strong enrichments were found for LOF de novo mutations in ASD and ID, largely driven by de novo mutations in SCN2A, a known gene for various developmental disorders, although no significant enrichments were found in schizophrenia or control populations (section 10)." (PMID 26196440, 2015). "AAV-EF1α-Cre-mCherry has also been utilized to delete Scn2a in mPFC and label excitatory cells in Scn2afl/fl mice to explore Nav1.2 function without a specific focus on schizophrenia." (PMID 39606727, 2024).
developmental and epileptic encephalopathy (19 papers, 2019 to 2026). An epilepsy associated with developmental impairment that may be due to either the underlying etiology or the superimposed epileptic activity, or both. "SCN2A-associated developmental and epileptic encephalopathy (SCN2A-DEE, Mendelian Inheritance in Man (MIM): #613721) is a rare monogenetic disorder characterized by early-onset (<3 months of age) seizures and profound developmental impairment." (PMID 40263630, 2025). "Early-onset SCN2A developmental and epileptic encephalopathy is caused by SCN2A gain-of-function variants." (PMID 40263630, 2025). "SCN2A mutations are associated with developmental and epileptic encephalopathy, episodic ataxia, and benign familial infantile seizures." (PMID 36011376, 2022). "Although SCN2A has been linked to other epileptic phenotypes, including developmental and epileptic encephalopathy (DEE) (see Section 3.2.2), BFNE was the first one to be described in relation to its pathogenic variants." (PMID 34679360, 2021). "De novo missense mutations in SCN2A can lead to neurodevelopmental disorders of various severity, including early-infantile developmental and epileptic encephalopathy (DEE), a rare severe disorder caused by Nav1.2 gain-of-function." (PMID 38939966, 2025). "In contrast, recently discovered de novo SCN2A mutations were found to be the most frequent causes of developmental and epileptic encephalopathy (DEE), manifesting as autism spectrum disorder, intellectual disability, and severe refractory seizures." (PMID 38003469, 2023). "In contrast, gain-of-function SCN2A missense mutations have recently been reported to be associated with early infantile seizures, such as developmental and epileptic encephalopathy (DEE), which usually occur as early as three months of life)." (PMID 36835631, 2023). "Mutations in SCN1A, SCN2A, SCN3A, and SCN9A genes are known to cause autosomal dominant developmental and epileptic encephalopathies, with haploinsufficiency as a primary mechanism." (PMID 40894531, 2025). "In this manuscript, we report the clinical and electrophysiological results of five patients of SCN2A‐related developmental epileptic encephalopathy (DEE)." (PMID 32400968, 2020).
Ohtahara syndrome (17 papers, 2012 to 2025). "For example, the variant identified in the fetus of family 1 in the SCN2A gene, had previously been reported as pathogenic and had been associated with developmental and epileptic encephalopathy 11 (DEE11) (OMIM #613721) which expedited the diagnosis." (PMID 39999070, 2025). "The remaining Ohtahara syndrome patient also harbored a novel SCN2A variant (p.Leu769Thr), classified as a variant of unknown significance due to the absence of a family study." (PMID 31572294, 2019). "It has been reported that phenotypic variability from benign infantile epilepsy to Ohtahara syndrome was observed in 3 affected individuals of a family with SCN2A variation." (PMID 35431799, 2022).
channelopathies (16 papers, 2018 to 2025). "The most frequent variants that cause DDE, associated with channelopathies, disrupt the function of the genes that encode voltage-dependent sodium and potassium channels, such as, for example, SCN2A and KCNQ2." (PMID 39858526, 2025). "Collaboration opportunities were also identified, including increased interaction with other channelopathies (e.g., SCN2A) and assistance in determining measurable clinical trial endpoints." (PMID 40830973, 2025). "Several genes, especially channelopathies, have been identified in patients who died of SUDEP including gene variants associated with seizures (e.g., SCN1A, SCN8A, SCN2A) or long QT-Syndrome (SCN5A, KCNH2, KCNQ1)." (PMID 40703772, 2025). "The current case enriches the existing prenatal phenotypic spectrum suggestive of SCN2A channelopathies, which are usually apparent postnatally with the development of seizures and neurocognitive abnormalities." (PMID 38255008, 2024). "In the case of six patients with variants in other channelopathy-related genes (SCN1A, SCN2A, SCN8A, and KCNQ2), the previous literature guided the choice of anti-seizure medication." (PMID 37645600, 2023). "In this study, we present data from two genetic human cellular models of SCN2A, to understand the channelopathy contributions to neurodevelopmental disorders." (PMID 38293651, 2023). "In channelopathies, seizures usually present as tonic (focal or general), such as those exhibited in KCNQ2, SCN2A and SCN8A genetic mutations." (PMID 34833120, 2021). "Following the identification of ventriculomegaly, complementary prenatal MRI could also be employed to reveal brain abnormalities characteristic of specific disorders such as SCN2A channelopathies." (PMID 38255008, 2024). "Certain cardiac abnormalities have also been sporadically reported in SCN2A channelopathies." (PMID 38255008, 2024). "Therefore, the identification of phenotypes such as ventriculomegaly is important as it could be used as an indication for an SCN2A channelopathy prenatally." (PMID 38255008, 2024). "Low-voltage fast activity followed by recruiting spikes or theta rhythms arising mainly from the central regions of either hemisphere followed by focal spike-wave complexes and prolonged focal or diffuse postictal attenuation could be seen in channelopathies, such as KCNQ2 and SCN2A channelopathy." (PMID 34833120, 2021). "Among molecularly diagnosed cases SCN1A, SCN2A, KCNQ2, SCN8A, and ATP1A2 were identified as channelopathy-related genes, representing 7 patients." (PMID 40083435, 2025). "This classification does not fully characterize the channelopathy, especially where an estimated 20–30% of ASD/ID patients develop late-onset seizures in addition to SCN2A deficiency." (PMID 38293651, 2023). "While SCN2A may not be alone in this potential, the development and critical assessment of SCN2A channelopathies in the context of experimental neuronal systems will be an essential step for expanding the palette of experimental systems needed to achieve a better molecular understanding of ASD." (PMID 32264956, 2020).
developmental delay (16 papers, 2013 to 2026). "Previous studies have suggested that over 80% of the SCN2A variants detected in patients with developmental retardation are located in the transmembrane region." (PMID 37152433, 2023). "91.7% (55/60) patients with de novo SCN2A variants had development delay, while only 16.7% (2/12) patients with inherited SCN2A variants had abnormal development." (PMID 35431799, 2022). "The 10 of 12 (83.3%) patients with inherited SCN2A variants had normal intelligence; however, the other 2 (2/12, 16.7%) patients had a developmental delay (Patient 10 and 48)." (PMID 35431799, 2022). "Among 60 patients with de novo SCN2A variants, 55 had development delay (91.7%, 55/60), and the remaining 5 patients had normal development." (PMID 35431799, 2022). "Most SCN2A variants located in transmembrane regions were related to patients with developmental delay." (PMID 35431799, 2022). "Among 72 patients with SCN2A variants, 57 patients (57/72, 79.2%) had varying degrees of developmental delay, and the other 15 patients had normal development." (PMID 35431799, 2022). "Within the DDDS data, heterozygous disease-causing variants in SCN2A, which is associated with global developmental delay with seizures, are correctly identified as dominantly-acting with scores of 0.85 on average." (PMID 28977528, 2017). "However, more than 90% of patients with de novo SCN2A variants showed developmental delay, which was identical to the reported studies." (PMID 35431799, 2022). "She had EIEE, profound developmental delay and microcephaly, features that could be accounted for alone by the SCN2A mutation." (PMID 26993267, 2016). "As the largest group of SCN2A carriers, SCN2A‐related infantile DEE presents as age‐dependent refractory epilepsy and has a poor prognosis with severe developmental delay." (PMID 32400968, 2020).
Seizure (16 papers, 2018 to 2025). A seizure is an intermittent abnormality of nervous system physiology characterized by a transient occurrence of signs and/or symptoms due to abnormal excessive or synchronous neuronal activity in the brain. "SCN2A variants are related to epileptic seizures, intellectual disability, autism spectrum disorders, and periodic ataxia." (PMID 37152433, 2023). "Epileptic seizures in patients with SCN2A variants occur early, mostly in the neonatal period or at early infancy." (PMID 37152433, 2023). "SCN2A variant patients developed focal seizures, of whom three patients showed comorbid spasms." (PMID 38174099, 2023). "However, when epileptic seizures occur in patients over 3-month-old, the identified SCN2A variants are usually LOF, and SCBs will aggravate epileptic seizure." (PMID 37152433, 2023). "In benign familial neonatal–infantile seizures patients, dominant point mutation is found in SCN2A gene, encode the alpha-subunit of the voltage-gated sodium channel NaV1.2." (PMID 33096746, 2020). "This is due only in part to the early start of seizures in DEE but also to the infantile manifestation of focal seizures in benign familial infantile epilepsies, which may be caused by variants in the PRRT2, KCNQ2, SCN2A, like in our cohort." (PMID 38328757, 2023). "For infants with epileptic seizures within 3 months after birth, SCBs, such as OXC, PHT, and CBZ are more effective, as the function of the variation of SCN2A is considered to be more likely to be GOF." (PMID 37152433, 2023).
Benign familial neonatal-infantile seizures (13 papers, 2011 to 2023). "Pathogenic variants of the SCN2A gene (MIM 182390) are associated with several epileptic syndromes ranging from benign familial neonatal-infantile seizures (BFNIS) to early infantile epileptic encephalopathy." (PMID 35053762, 2021). "Gain-of-function pathogenic variants of SCN2A underlie the Benign Familial Infantile-Neonatal Seizure (BFNIS) affecting children before three months of age and disappearing with age." (PMID 32899446, 2020). "Dominant mutations in SCN2A encoding Nav1.2 channels cause Benign Familial Neonatal-Infantile Seizures (BFNIS; prevalence: <1/1000,000), a mild seizure syndrome that responds positively to treatment with anti-epileptic drugs (AEDs), and generally remits by 1 year of age." (PMID 27242528, 2016). "Benign Familial Neonatal-Infantile Seizures (BFNIS or BFIS3; OMIM 607745) is a mild seizure syndrome caused by dominant mutations in SCN2A encoding for Nav1.2 channels." (PMID 26236192, 2015). "The genes SCN1A, SCN2A coding for the alpha subunit have been linked to specific idiopathic epilepsy syndromes such as generalized epilepsy with febrile seizures plus (GEFS+) and benign familial neonatal-infantile seizures (BFNIS), respectively." (PMID 25893123, 2015). "Missense mutations of SCN2A were also identified in a small percentage of GEFS+ patients and mainly in patients with benign familial neonatal-infantile seizures (BFNIS), a syndrome of mild seizures that remit during the first year of life without neurologic sequelae." (PMID 22798951, 2012).
Encephalopathy (13 papers, 2017 to 2026). Encephalopathy is a term that means brain disease, damage, or malfunction. "However, he has severe encephalopathy due to SCN2A mutation." (PMID 34149600, 2021). "However, while patients with SCN2A encephalopathy do display various types of focal seizures, absence‐like seizures are not commonly reported, suggesting a possible species‐specific effect." (PMID 32880951, 2021). "Therefore, our question for the ILAE Commission for Classification and Terminology is: when we talk about an SCN2A encephalopathy, are we referring to Dravet or Othahara syndrome?" (PMID 31907053, 2020).
neuroblastoma (13 papers, 2009 to 2024). Neuroblastoma (NB) is the most common solid, extracranial childhood tumor. "Co-cultivation of SH-SY5Y cells expressing PrPC with prion-infected mouse neuroblastoma (ScN2a) cells increased apoptotic cell death, as determined by activation of caspase-3." (PMID 30608982, 2019). "For example, TMAO has been shown to prevent the conversion of the normal cellular form of prion protein (PrPC) into its infectious form (PrPSC) in scrapies-infected mouse neuroblastoma ScN2a cells." (PMID 31843052, 2019). "Pyridine dicarbonitrile derivatives were firstly published in 2000 as a new class of rationally designed leads with activity against PrPSc replication in PrPSc-infected mouse neuroblastoma cells (ScN2a)." (PMID 28538692, 2017). "With an EC50 of only 22 nM against PrPSc accumulation in in PrPSc-infected mouse neuroblastoma (ScN2a-cl3) cells, compound 29 stood out among this series of derivatives and was found to be 100-fold more potent than the original lead compound." (PMID 28538692, 2017). "A diverse panel of aromatic compounds was screened in neuroblastoma cells persistently infected with PrPSc (ScN2a) for their ability to inhibit PK-resistant PrP (PrPRes) accumulation." (PMID 24400098, 2014). "Also of interest, AR-12 has been demonstrated in an in vitro setting to have a very rapid and robust effect on decreasing PrPSc levels in prion-infected neuroblastoma cells (ScN2a)." (PMID 27957385, 2016). "We next addressed whether PDI-inherent chaperone activities influence PrP conversion in prion-infected mouse neuroblastoma cells (ScN2a)." (PMID 19798432, 2009). "The lung cancer cells H460 only express SCN3A and SCN9A, whereas the neuroblastoma cells SHSY express SCN1A, SCN2A, SCN3A, and SCN9A." (PMID 31329011, 2019).
epilepsy syndrome (12 papers, 2014 to 2025). A syndrome that has a characteristic cluster of clinical features and/or lectroencephalographic (EEG) findings that reflect underlying epileptic activity. "Pathogenic variants or dysregulation in SCN2A were associated with a spectrum of related epilepsy syndromes and other neurological disorders." (PMID 34867172, 2021). "The aim of this work was to describe clinical features among five patients with concomitant SCN2A gene variants and cryptogenic epileptic syndromes, thus expanding the SCN2A spectrum of phenotypic heterogeneity." (PMID 35053762, 2021). "Similarly, variations in the SCN2A gene, responsible for the α-subunit of Nav1.2 channels, are linked to a range of epilepsy syndromes." (PMID 38837984, 2024). "SCN2A gene mutations are associated with several epileptic syndromes including ESES." (PMID 38397281, 2024). "SCN2A mutations are primarily associated with a variety of epilepsy syndromes." (PMID 30062040, 2018). "Variants in CHD2, CACNA1A, SCN2A, SCN9A, and other genes identified in our cohort have been previously linked to epileptic syndromes." (PMID 41302954, 2025). "Similarly, individual AD9 has dystonia and seizures and a duplication encompassing three genes, CACNB4, SCN1A and SCN2A, each responsible for epilepsy syndromes with or without movement disorders." (PMID 36781956, 2023).